MSTN (myostatin)
Diseases named in the same sentence as MSTN in open-access papers (continued):
Sharing a sentence is not in itself a finding about the gene and the disease.
Duchenne muscular dystrophy (44 papers, 2007 to 2026). Duchenne muscular dystrophy (DMD) is a neuromuscular disease characterized by rapidly progressive muscle weakness and wasting due to degeneration of skeletal, smooth and cardiac muscle. "This has led to the exploration of the use of myostatin inhibitors in the treatment of Duchenne muscular dystrophy and other conditions associated with muscle weakness." (PMID 40026240, 2025). "Systemic myostatin inhibition led to increased skeletal muscle mass and strength in control C57 Bl/6 mice and in the dystrophin-deficient mdx model of Duchenne muscular dystrophy." (PMID 20161803, 2010). "Peptides derived from the first α-helix of myostatin pro-domain are relatively potent inhibitors of myostatin, and myostatin pro-domain fused to antibody Fc part can increase muscle mass in mdx mice, a mouse model for Duchenne muscular dystrophy." (PMID 34495310, 2021). "Myostatin antagonists are being developed as therapies for Duchenne muscular dystrophy due to their strong hypertrophic effects on skeletal muscle." (PMID 30368252, 2018). "It is imperative to establish the safety of myostatin inhibition on the dystrophic heart because cardiomyopathy is nearly ubiquitous by 18 years of age in humans with Duchenne muscular dystrophy." (PMID 20161803, 2010). "Similarly, using this method to anchor myostatin propeptide to the surface of EVs can improve muscle function and provide new possibilities for treating duchenne muscular dystrophy (DMD)." (PMID 36175866, 2022). "Moreover, they found that the same patients with Duchenne muscular dystrophy also have reduced myostatin expression levels in skeletal muscle." (PMID 35922829, 2022). "More recently, two independent groups reported that myostatin could be a quantifiable biomarker to monitor drug response in several neuromuscular diseases including Duchenne muscular dystrophy and myotubular myopathy." (PMID 32906621, 2020). "Previous preclinical studies in the mdx mouse model of Duchenne muscular dystrophy targeting the myostatin pathway have utilized neutralizing antibodies, myostatin propeptide injection and recombinant adeno-associated virus (AAV) mediated expression of a myostatin inhibitor from multiple tissues." (PMID 20161803, 2010). "Initial clinical investigations of myostatin inhibitors in muscular dystrophies, particularly Duchenne muscular dystrophy (DMD), yielded disappointing results." (PMID 40368588, 2025). "For example, a study investigated the engineering approach of inhibiting myostatin to improve the outcome of Duchenne muscular dystrophy (DMD)." (PMID 38922501, 2024). "Pharmacological manipulation of myostatin has already been tested as a therapeutic approach: Myostatin inhibition may theoretically be beneficial in diseases with muscle weakness such as Duchenne muscular dystrophy or rheumatoid arthritis and was already tested." (PMID 33895875, 2021). "In addition, a mouse anti-myostatin antibody increases muscle mass and improves muscle strength and contractility in the mdx mouse model of Duchenne muscular dystrophy, and its humanized equivalent, domagrozumab (PF-06252616), increases muscle volume in cynomolgus monkeys." (PMID 30922397, 2019). "Several strategies based on the myostatin-follistatin pathway are currently in clinical trials for muscle pathologies such as Duchenne muscular dystrophy (DMD), Becker muscular dystrophy and inclusion body myositis but have yet to be initiated for SMA." (PMID 28768735, 2017). "Building on these results, a number of strategies including the use of Myostatin inhibitors or antisense oligonucleotides to manipulate myostatin pre-mRNA splicing are being developed for the treatment of muscle-wasting disorders such as Duchenne muscular dystrophy." (PMID 24827585, 2014).
Duchenne muscular dystrophy (continued). "The use of neutralizing antibodies to myostatin improved muscle disorders in rodent models of Duchenne muscular dystrophy (DMD), limb girdle muscular dystrophy 2F (Sgcg−/−), and amyotrophic lateral sclerosis (SOD1G93A transgenic mouse)." (PMID 22500226, 2012). "Furthermore, a study on Duchenne muscular dystrophy (DMD) demonstrated that GCs counteracted myostatin inhibitors and exhibited an atrophic phenotype." (PMID 40806744, 2025). "Indeed, inhibition of myostatin in the mdx mouse, a model of Duchenne muscular dystrophy (DMD), accelerates the development of dilated cardiomyopathy." (PMID 21931616, 2011). "Some authors advocate that certain neuromuscular diseases, such as Duchenne muscular dystrophy (DMD) and congenital myotubular myopathy, might belong to this group, so that these patients may be less responsive to therapeutic myostatin inhibition." (PMID 35727341, 2022). "Postnatally, myostatin inhibition achieved by neutralizing antibodies directed against myostatin administered in normal C57 Bl/6 mice and in the mdx mouse model of Duchenne muscular dystrophy leads to muscle growth due to hypertrophy and not hyperplasia." (PMID 20161803, 2010). "Demagrozumab, another monoclonal anti-myostatin antibody, was developed and tested in phase 2 clinical trial in boys with Duchenne muscular dystrophy, but as it only resulted in non-significantly increased muscle volume and no improvement in muscle function, the trial was terminated early." (PMID 40725168, 2025). "Similarly, in boys with Duchenne muscular dystrophy, a trend in increased spine BMD was observed with an increasing concentration of ACE-031, a fusion protein of activin receptor type IIB and IgG1-Fc, which binds myostatin." (PMID 40725168, 2025). "Many investigators have evaluated the effects of myostatin inhibition in muscle disease models such as cancer cachexia, CKD, Duchenne muscular dystrophy (DMD), and amyotrophic lateral sclerosis." (PMID 37830636, 2023). "This study aimed to determine whether an oral administration of Lactobacillus casei expressing modified human myostatin (BLS-M22) could elicit sufficient levels of myostatin-specific antibody and improve the dystrophic features of an animal model of Duchenne muscular dystrophy (DMD; mdx mouse)." (PMID 36012334, 2022).
muscle atrophy (41 papers, 2007 to 2025). The loss of muscle tissue due to inactivity or disease. "It is known that myostatin-mediated human skeletal muscle atrophy is associated with sarcomeric protein loss, as well as enhanced expression of the ubiquitin E3 ligases atrogin-1 and MURF1." (PMID 36901894, 2023). "Myostatin can be inhibited by antibodies or compounds, which are currently being investigated for their therapeutic potential in clinical trials such as muscle atrophy associated with cancer and muscular dystrophy." (PMID 36901894, 2023). "Glucocorticoid-induced skeletal muscle atrophy is associated with the upregulation of myostatin gene expression, indicating that myostatin plays a crucial role in dexamethasone-induced muscle atrophy." (PMID 32709024, 2020). "The inhibition of myostatin also protects against muscle atrophy due to glucocorticoid treatment and the effect of glutamine on prevention of glucocorticoid-induced skeletal muscle atrophy is associated with myostatin suppression." (PMID 19412331, 2007). "Additional clinical data on patients with muscle atrophy-linked neuromuscular disorders reveal that patients with advanced muscle wasting and atrophy have significant decreases in circulating myostatin levels and myostatin expression in muscle biopsies in contrast to other studies." (PMID 33854530, 2021). "In this study, we designed and implemented an experimental mouse model mimicking muscle atrophy driven by CKD and then investigated the effects of MSTN-ASO (KMM001) on CKD-induced muscle atrophy." (PMID 40243849, 2025). "To investigate the therapeutic potential of MSTN-ASO in counteracting CKD-induced muscle atrophy, we administered MSTN-ASO subcutaneously to C57BL/6j mice." (PMID 40243849, 2025). "Data on myostatin, a muscle growth suppressor and a member of the myokine family, regarding its role in age‐related muscle atrophy in various human cohorts are conflicting." (PMID 40162588, 2025). "The authors of this study also showed a positive correlation between MSTN levels and BMI and body fat of the subjects, thus confirming the relationship between high MSTN levels and muscle atrophy." (PMID 38542721, 2024). "In accordance with the functional classification of a GO term, a series of CGs was enriched into GO terms related to muscle development regulation, such as cell growth regulation (LTBP4) and skeletal muscle atrophy (MSTN)." (PMID 35883386, 2022). "As excessive myostatin accelerates muscle atrophy, inhibitors of myostatin have been attracting attention as potential targets for muscle atrophy therapeutics." (PMID 32106603, 2020). "The myostatin signaling pathway has emerged as a major target for symptomatic treatment of muscle atrophy." (PMID 29546591, 2018). "Therapeutics for muscle atrophy currently in preclinical or clinical development include inhibitors of myostatin (also known as Growth and Differentiation Factor 8 or GDF8), a secreted growth factor that negatively regulates muscle mass." (PMID 29396542, 2018). "Myostatin inhibitors have been intensively studied as pharmaceutical targets for muscle atrophy and mice treated with anti-myostatin antibodies have increased muscle mass and improved muscle insulin sensitivity." (PMID 28222718, 2017). "The correlation between serum myostatin levels and muscle mass and reports of elevated myostatin levels in the elderly suggest that myostatin inhibitors may be effective in preventing muscle atrophy in actual clinical practice." (PMID 39940810, 2025). "Therefore, this study explored the use of KIC as a therapeutic agent for CAC‐induced muscle atrophy by targeting myostatin." (PMID 40810552, 2025). "Therefore, Myostatin is considered to be an important factor in developing medicines for use in muscle atrophy therapy." (PMID 35565825, 2022). "Myostatin can inhibit normal muscle growth, and targeting myostatin may be used as a promising strategy to increase muscle mass in elderly or patients with muscle atrophy." (PMID 36325361, 2022).
muscle atrophy (continued). "High expression of MSTN is usually found in muscle atrophy or senile muscle diseases." (PMID 34829990, 2021). "Indeed, flavonoids have been proposed as potential candidates to treat muscle atrophy due to their role in improving mitochondrial function and decreasing proteolysis through the downregulation of myostatin and the atrogenes MURF-1 and atrogin-1." (PMID 34067004, 2021). "FMN has an anti‐inflammatory effect and inhibition of myostatin expression in CKD muscle atrophy." (PMID 33405354, 2021). "Collectively, our results provide evidence to suggest that microRNA-208b plays a role in inducing myostatin expression after spinal cord injury in humans and may contribute to the complex regulation of skeletal muscle atrophy in tetraplegia." (PMID 26603456, 2015). "Moreover, myostatin expression was inversely correlated with microRNA-208b and microRNA-499-5p in human skeletal muscle following spinal cord injury, coincident with skeletal muscle atrophy." (PMID 26603456, 2015). "Activin receptor (ACVR2) antagonists have succeeded in blocking the interaction between MSTN and ACVR2, thus preventing the development of MSTN-induced muscle atrophy." (PMID 39409095, 2024). "Like MSTN inhibitors, the antagonists of MSTN’s receptor ACVR2s are capable of blocking the interaction between MSTN and ACVR2, therefore it inhibits MSTN induced muscle atrophy." (PMID 34553120, 2021). "C20-5HT and C22-5HT were isolated from CSE as the major compounds contributing to the MSTN inhibition, suggesting the potential of CSE, C20-5HT, and C22-5HT being developed as agents to combat muscle atrophy and metabolic syndrome." (PMID 34063650, 2021). "However, considering the general failure to treat human muscle diseases so far, a more specific myostatin inhibition may be required that decreases or eliminates the effect on other molecular pathways related to myostatin signaling for the continued relevance in muscle atrophy diseases." (PMID 33802348, 2021). "In summary, the results show that CSE has the MSTN-inhibitory capacity, and C20−5HT and C22−5HT are active components of CSE-suppressing MSTN activity, suggesting the potential of CSE, C20−5HT, and C22−5HT being developed as agents to combat muscle atrophy and metabolic syndrome." (PMID 34063650, 2021). "As skeletal muscle atrophy in CKD can result from several interrelated mechanisms leading to an imbalance between protein synthesis and degradation, we further investigated whether the beneficial effects of FGF19 could implicate pathways such as the ubiquitin–proteasome or myostatin." (PMID 37015932, 2023).
type 2 diabetes (41 papers, 2009 to 2026). "MSTN mutation leads to a decrease in fat content and an increase in the lean meat rate, which enhances the metabolism efficiency and reduces type 2 diabetes risk." (PMID 35245313, 2022). "Interestingly, type 2 diabetic patients have an up-regulated plasma myostatin associated with increased body mass index, higher fasting plasma glucose, and blood insulin sensitivity." (PMID 25279796, 2014). "FST has been found to alleviate myostatin-induced bone degeneration in Type 2 diabetes mellitus (T2DM) mice." (PMID 39066929, 2024). "To address previous limitations in the literature, we excluded adults with type 2 diabetes or other end‐organ dysfunction and quantified serum myostatin levels using LC–MS/MS." (PMID 39261976, 2024). "In our study, we found that the abundance of Pseudoflavonifractor, a type 2 diabetes-related flora, was decreased in MT cattle, indicating that MSTN can regulate metabolism by regulating intestinal flora." (PMID 35245313, 2022). "Targeting the myostatin signaling pathway proved effective also in reducing fat mass, an effect that has been clearly seen in obese individuals with type 2 diabetes treated with bimagrumab." (PMID 35727341, 2022). "As a result, in this study, we showed that myostatin and irisin are effective in sarcopenic and SO patients with type 2 diabetes." (PMID 34190188, 2021). "Thereby, myostatin regulates bone formation, and blocking myostatin improves fracture healing in patients with type 2 diabetes." (PMID 33919377, 2021). "Myostatin is a negative regulator of muscle mass and its inhibition represents a promising strategy for the treatment of muscle disorders and type 2 diabetes." (PMID 33452345, 2021). "In the study by Yamakage at al., dapagliflozin add-on therapy in patients with type 2 diabetes reduced myostatin levels significantly, and they maintained skeletal muscle mass." (PMID 32796600, 2020). "Elevations in myostatin expression have been observed repeatedly in humans with muscle wasting conditions and in metabolic disorders like type 2 diabetes." (PMID 32652899, 2020). "It is expected that inhibition of myostatin function can be an effective alternative approach in enhancing insulin sensitivity and thus for potential prevention and treatment of type 2 diabetes." (PMID 28432282, 2017). "Levels of myostatin are positively correlated with pro-inflammatory factors in both chronic kidney disease and type 2 diabetes, and a high expression of myostatin has been found in RA synovial membranes." (PMID 29276516, 2017). "In conclusion, we measured the serum myostatin and blood biochemistry variables in type 2 diabetic patients and their age and gender matched controls, and found that patients with DM had lower serum myostatin level." (PMID 25254550, 2014). "Myostatin levels are elevated in serum from obese individuals and patients with type 2 diabetes have elevated myostatin expression in the skeletal muscle tissue." (PMID 25104880, 2014). "Patients with type 2 diabetes had higher levels of muscle myostatin mRNA content than the control subjects." (PMID 24454989, 2013). "The plasma myostatin concentration was slightly elevated in patients with type 2 diabetes 5.1 (4.6–5.7) μg/L compared to 4.5 (4.1–5.0) μg/L in control subjects." (PMID 22615949, 2012). "We evaluated the possible metabolic role of myostatin in patients with type 2 diabetes and healthy controls." (PMID 22615949, 2012). "Patients with type 2 diabetes had 1.4 (P<0.01) higher levels of muscle myostatin mRNA content than the control subjects." (PMID 22615949, 2012). "The healthy controls and patients with type 2 diabetes were divided into low (QL) and high (QH) muscle content of myostatin mRNA and the fasting glucose, insulin, HOMA2-IR, and plasma IL-6 levels were compared." (PMID 22615949, 2012). "The present study demonstrates that skeletal muscle myostatin mRNA is elevated in patients with type 2 diabetes when compared to healthy control subjects." (PMID 22615949, 2012).
type 2 diabetes (continued). "An inhibitory association is supported by a gene expression study in which an transcriptomic array revealed an increased myostatin expression in skeletal muscles of patients with type 2 diabetes." (PMID 22615949, 2012). "Moreover, both type 1 and type 2 diabetes patients were shown to have higher serum MSTN concentrations when compared to healthy counterparts." (PMID 39340593, 2025). "Myostatin has been recognized as a target of inhibitors and neutralizing antibodies and also physical exercise to improve muscle mass and strength, body composition, as well as bone quality and metabolic dysfunctions, including type 2 diabetes." (PMID 35631274, 2022). "However, the metabolic effect of myostatin appears to be overruled by other factors in patients with type 2 diabetes." (PMID 22615949, 2012). "However, the metabolic effect of myostatin appears to be overruled by other factors in full-blown type 2 diabetes." (PMID 22615949, 2012). "Finally, the results of this study suggest that myostatin disruption might be a promising strategy for the treatment of type 2 diabetes and related metabolic diseases." (PMID 29228005, 2017). "Therefore, we recruited 246 type 2 diabetic patients and 82 age and sex-matched non-diabetic controls to investigate the association of serum myostatin with their anthropometric and metabolic status." (PMID 25254550, 2014). "In our GK model of type 2 diabetes, we confirmed an increase in plasma and SKM levels of myostatin and 8-OHdG; a correlation appears that exists between plasma levels of myostatin and 8-OHdG, a known marker of oxidative stress (r = 0.71)." (PMID 30510624, 2018). "Gene chip analysis found increased MSTN mRNA levels in skeletal muscle biopsy samples from individuals with type 2 diabetes and their nonobese but hyperinsulinemic relatives." (PMID 35780124, 2022). "Therefore, if a causal relationship exists between myostatin and metabolism, it appears that the negative, regulatory effects of myostatin on metabolism are overruled by other factors in advanced type 2 diabetes." (PMID 22615949, 2012).